IL6 (interleukin 6)
Diseases named in the same sentence as IL6 in open-access papers (continued):
Sharing a sentence is not in itself a finding about the gene and the disease.
myeloma (continued). "We here showed that hypoxia-induced miR-210 increased the mRNA expression of VLA-4, CXCR4, IL-6 and TGF-β in myeloma cells." (PMID 30108468, 2018). "Other myeloid cells involved in myeloma progression, such as megakaryocytes and eosinophils, are also involved in the survival of plasma cells by production of IL-6 and APRIL that promote the survival of myeloma cells." (PMID 30405034, 2018). "Some studies have indicated that bone marrow stromal cell-derived cytokine Interleukin-6 (IL-6) can upregulate MCL-1 and BCL-XL expression in myeloma cells, thus providing a possible mechanism of resistance to venetoclax." (PMID 30406027, 2018). "Increased levels of key cytokines have also been shown to progressively increase from controls to smouldering myeloma to multiple myeloma including CXCL8 (IL-8), IL-10, TNFα, IL6 and IFNγ." (PMID 28389623, 2017). "On the other hand, stimulation with IL-6 increases the expression and secretion of FGF-beta by the myeloma cell lines." (PMID 28099912, 2017). "IL-6 induces activation of the PI3K/AKT pathway, and is involved in protection against apoptosis and in enhanced proliferation of multiple myeloma cells." (PMID 28903416, 2017). "The up-regulation of miR-21 is shown to facilitate the activation of IL6-JAK-STAT pathway and STAT3, which is a major mediator of growth, proliferation and survival of myeloma cells conferred by bone marrow microenvironment." (PMID 28458781, 2017). "In multiple myeloma, growth factor cytokines such as IGF-1 and IL-6 mediate a complex signaling network which stimulates the proliferation of MM cells." (PMID 29254208, 2017). "IL-17 induces the expression of some chemokines and cytokines including IL-6 and TGF-β, in a variety of cell types, including the BMSCs, implying that the correlation between IL-6, TGF-β, and IL-17 is responsible for the progression of myeloma." (PMID 28881756, 2017). "Interleukin-6 (IL-6)-activated Signal Transducer and Activator of Transcription 3 (STAT3) facilitates survival in the multiple myeloma cell line INA-6 and therefore represents an oncogenic key player." (PMID 28801664, 2017). "It retained its activity in the presence of the soluble cytokines IL-6 and IGF-1 and when plasma cells were co-cultured with BMSCs from myeloma patients." (PMID 28633670, 2017). "In multiple myeloma, stromal-derived IL-6 stimulates FGF2 expression in tumor cells, which in turn stimulates the secretion of IL-6." (PMID 27007053, 2016). "In myelomas, p38 MAPK inhibitors diminished IL-6- and VEGF-mediated paracrine effects, thereby inhibiting the proliferation of tumor cells." (PMID 27413117, 2016). "Another type I inhibitor, SD-208, has been reported to abrogate secretion of IL-6 and VEGF from myeloma-derived bone marrow stromal cells while also reducing tumor cell growth." (PMID 27655636, 2016). "Interestingly, treatment with IL-6 or supernatant from bone marrow stromal cells resulted in further decrease in miR-23b expression in MM and WM cells, indicating that the human bone marrow microenvironment has a prominent role in the modulation of miR-23b levels in myeloma cells." (PMID 26771806, 2016). "In contrast, VLA‐5‐positive myeloma cells were non proliferative, mature myeloma cells, non‐responsive to IL‐6 and secreted higher amounts of M‐protein than VLA‐5‐negative myeloma cells." (PMID 27734595, 2016). "Compared to CD45- myeloma cells, CD45+ myeloma cells with an activated JAK/STAT3 pathway are particularly sensitive to JAK2 inhibitor which inhibits IL-6-induced JAK and STAT3 phosphorylation." (PMID 25781885, 2015). "Although CD45 plays an important role in regulating the IL-6-induced proliferation, the question of the downstream signaling difference of CD45 isoforms in myeloma cells remains poorly documented." (PMID 25781885, 2015).
myeloma (continued). "In multiple myeloma cells, various investigators have identified FYN, HCK and LYN in co-immunoprecipitates with GP130, and stimulation of these cells with IL6 results in increased activation of these SFKs." (PMID 26087188, 2015). "In myeloma cell IL-6 induced proliferation, activation of Src family kinases is required through CD45 molecules as well as activation of STAT3 and MAPK via the IL-6/IL-6 receptor complex." (PMID 26464811, 2015). "Since IL-6 and VEGF are secreted by both myeloma and stromal cells, we studied the level of IL-6 and VEGF in co-culture media." (PMID 26015393, 2015). "Levels of the cytokines IL-6 and VEGF, secreted by the myeloma cells and the surrounding bone marrow stromal cells, are reduced by numerous HDAC inhibitors which is in line with results from our experiments." (PMID 26015393, 2015). "Numerous naked antibodies have been tested in preclinical myeloma models, and antibodies against six antigens, that is, CD38, CD74, CD40, SLAMF7, IL-6, and IGF-1R, have been examined in clinical trials." (PMID 26649299, 2015). "Various soluble factors have been identified in the signaling crosstalk between myeloma and stromal cells including IGF-1, IL6, DKK-1, RANKL and activin A." (PMID 25887188, 2015). "The mechanism by which the GP130/HCK-containing complex promotes IL6-induced activation of ERK and PI3K in multiple myeloma cells is dependent on the adaptor proteins GAB1 and GAB2, which are constitutively associated with HCK." (PMID 26087188, 2015). "Bone marrow derived IL-6 and APRIL have been shown to be major environmental-derived factors supporting the growth and drug-resistance of multiple myeloma, and also to support the survival of long-lived bone marrow plasma cells." (PMID 25272036, 2014). "IL-6 has a role in multiple myeloma development, as demonstrated by its ability to induce apoptosis by blocking the IL-6R/STAT3 pathway in vitro and the resistance of IL-6−/− mice to plasmacytoma induction." (PMID 24901008, 2014). "In myeloma cells established from bone marrow of a mouse (SNU_MM1393_BM), phosphorylated form of Erk (p-ERK) was increased when treated with IL-6 only and combination of IL-6 and sIL-6R, but phosphorylated form of Akt (p-AKT) was not." (PMID 25343143, 2014). "IL-6 which produced by both BMMSC and myeloma cells is a key cytokine in the pathogenesis and disease progression of MM." (PMID 25788856, 2014). "Together, these results indicate that MOPC315.BM cells are supported by IL-6 and APRIL, as have been previously reported for multiple myeloma." (PMID 25272036, 2014). "Some cytokines such as IL-7, IL-3, IL-6, TNF-α produced by myeloma cells can inhibit the differentiation and activativity of osteoblasts and induce osteoblasts apoptosis." (PMID 25788856, 2014). "Inhibition of tumor cell proliferation by SL1026 and SL1033 was demonstrated in U266B1 myeloma, HepG2 hepatoma, and U87MG glioma cells, and the potency of SOMAmer inhibition of IL-6 was equal to or greater than tocilizumab inhibition of IL-6Rα in all cases." (PMID 24415766, 2014). "We show that MOPC315.BM myeloma cells resemble an aggressive tumor stage, but are still supported by APRIL and IL-6." (PMID 25272036, 2014). "Multiple myeloma is a bone marrow plasma cell tumor which is supported by the external growth factors APRIL and IL-6, among others." (PMID 25272036, 2014). "In multiple myeloma, BMSCs up-regulate the secretion of several factors (IL-6, IGF-1, VEGF, FGF, SDF-1 and TNFα) as a result of their direct interaction with myeloma cells through integrins and soluble factors produced by myeloma cells." (PMID 24304929, 2013). "Consistent with this, monoclonal antibodies to CD40 block CD40L-induced NFκB activation as well as IL-6 and VEGF secretion in cultures of multiple myeloma cells and bone marrow-derived stromal cells." (PMID 23905066, 2012).
myeloma (continued). "Immunological inhibitory cytokines, such as TGF-β, IL-10, IL-6 and VEGF, which are produced from myeloma cells, can modulate antitumor host immune response, including the abrogation of DC function, by constitutive activation of STAT3." (PMID 22481968, 2012). "For example, IL-1β, IL-6, IL-10, IFN-α, IGF-1 and TGF-γ promote proliferation of multiple myeloma cells, whereas IFN-β1 and APO-1/FAS inhibit the growth of multiple myeloma cells." (PMID 22792345, 2012). "In addition to causing bone disease, inhibition of osteoblast differentiation by DKK1 may also promote MM growth, since mature osteoblasts can suppress myeloma growth, whereas immature osteoblasts express high levels of IL-6, a central growth and survival factor for myeloma plasma cells." (PMID 22363428, 2012). "Studies investigating microRNAs in MM began in 2007 with the discovery that interleukin 6 (IL-6) indirectly induces the transcription of miR-21 through signal transducer and activator of transcription 3 (STAT3) transcription in the human myeloma cells line." (PMID 23259069, 2012). "PRL-3 expression was reported to be regulated at transcriptional level by mitogenic cytokines, such as IL-6, IL-21, HGF or IGF-1 in myeloma cell lines, or as TGF-β in colon cancer cell lines." (PMID 21466710, 2011). "6-OAP abrogates the protective effects of IL-6 and IGF-I on myeloma cells through inhibition of Jak2/Stat3 and Akt signal pathways, respectively." (PMID 21755010, 2011). "Studies demonstrate that BM microenvironment, including BM stromal cells (BMSC), paracrine signaling loops involving cytokines interleukin-6 (IL-6) and insulin-like growth factor-I (IGF-I), plays pivotal roles in myeloma pathogenesis and drug resistance." (PMID 21755010, 2011). "IL-6 mediates growth and survival of human myeloma cells through the MEK/MAPK and Jak/Stat signaling pathways, and IL-6 confers protection against dexamethasone-induced apoptosis via activation of the protein tyrosine phosphatase, SHP2." (PMID 20204067, 2010). "We have shown that a weak autocrine IL-6 production is sufficient to trigger cell cycling on myeloma cell lines (HMCL), whereas survival of those cells requires large exogenous IL-6 concentrations." (PMID 20465808, 2010). "They showed that IL-6-stimulated VEGF expression in and secretion from myeloma cell lines and in plasma cells purified from the marrow of patients with MM as well." (PMID 20204067, 2010). "It has been reported, for example, in myeloma, to suppress angiogenic factors such as vascular endothelial growth factor (VEGF), and inflammatory genes such as TNF-alpha and IL-6." (PMID 20181085, 2010). "PU-H71 showed comparable anti-myeloma activity in IL-6 dependent cell line INA-6 and the other IL-6 independent cell lines." (PMID 20977755, 2010). "In multiple myeloma, osteoclastogenic factors, such as interleukin-6, RANKL and macrophage inflammatory protein 1α, are abundantly expressed by myeloma cells." (PMID 20010942, 2010). "This upregulation occurs through cytokine signaling of IL-6, TNF-β, and insulin-like growth factor (IGF), all of which are increased due to interaction of myeloma cells with stromal cells." (PMID 20671999, 2010). "The starting point of this study was our observation that IL-6, IL-21 and TNF-α induced expression of BCL3 in the myeloma cell lines OH-2 and IH-1." (PMID 19191868, 2009). "Downregulation of vascular endothelial growth factor (VEGF) beta, IL6 and BCL2 were also evident, as previously identified in human multiple myeloma cells following bortezomib-induced apoptosis." (PMID 17895889, 2007). "However, the inhibitory effect was decreased with the addition of IL-6 and IGF-1, two primary compounds for inducing the PI3K signaling pathway in myeloma cells." (PMID 40922746, 2025).
myeloma (continued). "The regulatory mechanism of miR-21-5p transcription has been reported to be stimulated by IL-6 and signal transduction and activator of transcription 3 (STAT3) in both human multiple myeloma cell lines and bovine cumulus cells; however, it has never been reported in primary cultured FLS." (PMID 40461641, 2025). "Additionally, interactions with immature DCs release cytokines like IL-6, increasing RANK-L and M-CSF production by stromal cells, osteoblasts, and myeloma cells." (PMID 40313957, 2025). "This pro-proliferative sign is not specific to pDCs, as mesenchymal stem cells (MSCs) are another cell type that support multiple myeloma proliferation directly via the suppression of T cells through the PD-1 axis, and others such as the DKK1+ MM cells and Il-6-producing undifferentiated MSCs." (PMID 41374932, 2025). "Additionally, IL-6 stimulation upregulates FGF2 secretion in keratinocytes, myeloma cells, and basal cells through the IL-6/STAT3 pathway." (PMID 38338991, 2024). "Mcl-1 is classified as an antiapoptotic protein that is overexpressed in many types of IL-6-treated cancer cells, including prostate cancer, myeloma, gastric cancer, and cholangiocarcinoma cells, but not in control cells." (PMID 39272918, 2024). "We neither tracked IL-6 levels during experiments nor checked IL-6 levels before transplantation of myeloma cells." (PMID 38713510, 2024). "Depending on the cell type under study, a feedback circuit between IL-6 and HO-1 has previously been described; it is positive in human multiple myeloma cells and negative in hepatoma cells." (PMID 39100660, 2024). "Inhibition of IL-6 mediated signaling by decreasing the expression of its receptor at the transcription level via AMPK, mTOR, and miR-34a is one of the newer mechanisms that suggest metformin as a potential treatment for multiple myeloma." (PMID 38675438, 2024). "The bone marrow microenvironment plays a crucial role in the progression of multiple myeloma by secreting a range of cytokines and growth factors (e.g., IL-6, VEGF, TGF-β, IGF-1, CXCL12) that support the survival, proliferation, and resistance to apoptosis of myeloma cells." (PMID 38831183, 2024). "However, in both IL-6 independent cell lines and IL-6 reliant cell line INA-6, PU-H71 has demonstrated comparable anti-myeloma efficacy." (PMID 39564119, 2024). "CSF3 promoted the proliferation of myeloma cells, although it did not affect the expression of IL-6 and IL-6R, indicating that IL-6 does not mediate the proliferative effects of CSF3." (PMID 37250588, 2023). "Besides modulating chemoresistance, miR-197-3p targeted Interleukin (IL)-6 and suppressed IL-6/JAK/STAT3 pathways, counteracting the selective proteasome inhibitor Bortezomib’s resistance to multiple myeloma." (PMID 36769824, 2023). "Moreover, release of IL-6 and TNF-α by TAMs increases the vascular leakiness of newly formed tumor vessels in Vk*MYC myeloma mice thus facilitating the entrance of single plasma cell clones into the blood circulation." (PMID 37744361, 2023). "However, an important advance in developing a humanized mouse model for myeloma engraftment occurred with the report of the MISTRG6 model, a mouse with human IL-6 that showed successful engraftment in >80% primary MM samples." (PMID 38001595, 2023). "Myeloma progenitors in the BM microenvironment take advantage of both myeloma-cell-derived (autocrine) and tumour microenvironment-derived (paracrine) IL-6 released by non-malignant bystander cells such as bone marrow stromal cells (BMSCs)." (PMID 37808081, 2023). "The suppression of IDO1 induction by carfilzomib could enhance its therapeutic activity in myeloma, a problem potentially exacerbated by the apparent ability of carfilzomib alone to induce some IL1B and IL6 expression." (PMID 35371018, 2022).
myeloma (continued). "Interleukin 6 (IL-6), vascular endothelial growth factor (VEGF), tumor necrosis factor-alpha (TNF-α), C-reactive protein (CRP), and lactate dehydrogenase (LDH) were also involved in the pathogenesis of myeloma." (PMID 35919637, 2022). "In multiple myeloma, PADI2 is the most up-regulated transcript in bone marrow mesenchymal stem cells, which may mediate the up-regulation of IL-6 expression by inducing histone citrullination, enabling tumor cells to acquire resistance to anti-tumor drugs." (PMID 36479196, 2022). "Mechanistically, the pro-inflammatory cytokines IL-6 and tumor necrosis factor alpha (TNFα) secreted by CD169+TAMs, increase vascular leakage and downregulate CD138-mediated cell adhesion; thus, driving myeloma intravasation." (PMID 35847862, 2022). "In addition, IL-6 enhances bone resorption by promoting the proliferation of Dickkopf-1 (DKK-1)-secreting myeloma cells, but DKK-1 secretion is blocked after IL-6 neutralizing agents." (PMID 35328533, 2022). "MDSC production of S100A9, a calcium-binding protein that promotes the release of TNF-α, IL-6, and IL-10 in autocrine pathway through TLR4 interaction, attracts myeloma cells in the TME and supports myeloma cell growth via the activation of the canonical NFκB pathway." (PMID 36726975, 2022). "In vivo multiple myeloma mouse model, bone marrow stromal cell (BMSC)-derived exosomes contain oncoproteins, cytokines, adhesion molecules, such as IL-6, CCL2, and fibronectin, which can induce the survival, proliferation, and migration of multiple myeloma cells." (PMID 35692747, 2022). "Moreover, CXCL12 supports MM growth through the induction of interleukin-6 (IL-6) and vascular endothelial growth factor (VEGF) secretion and increases invasion and matrix metalloproteinase (MMP) secretion in myeloma PCs." (PMID 35064098, 2022). "Several studies have demonstrated that inhibition of the IL6R/STAT3 pathway with anti-IL6, IL6R antagonists, or JAK-inhibitors induced apoptosis of human myeloma cell lines in vitro and enhanced the antitumor activity of other anti-myeloma drugs in vivo, attenuating chemoresistance." (PMID 34205916, 2021). "Additionally, Chong and colleagues demonstrated that IL-6 triggers STAT3 activation and drives the transcription of PRL-3 (an oncogenic phosphatase overexpressed in multiple myeloma)." (PMID 35053027, 2021). "In MM, IL-6 is the key proliferation factor for immature plasma cells but not a differentiation factor since myeloma cells lack terminal differentiation." (PMID 33923357, 2021). "Some myeloma cell lines have been shown to be capable of autocrine and paracrine IL-6 secretion, while others do not express IL-6." (PMID 33808304, 2021). "Previous studies have shown that H19 promotes cancer development through different mechanisms, as examples: in gastric cancer through Fas-related protein, in cholangiocarcinoma through IL-6 and CXCR4, in colorectal cancer through HMGA1, and in multiple myeloma through P50/P65." (PMID 34843522, 2021). "IL-6, in turn, may stimulate VEGF secretion in a subset of myeloma cells, indirectly promoting angiogenesis." (PMID 33531904, 2021). "Moreover, MMSET is a strong co-activator of NF-κB, and their cooperation activates the expression of downstream genes, including IL-6, IL-8, VEGFA, cyclin D, Bcl-2, and survivin, to protect myeloma cells from chemotherapy-induced apoptosis." (PMID 33420361, 2021). "In contrast to MO-DCs, there is high level of endogenous IL-6 expression in myeloma cells which was not further increased by stimulation with LPS, and no significant induction of IL-6 when NonO levels were decreased." (PMID 32765503, 2020). "Moreover, soluble factors such as IFN-γ, IL-6, and indoleamine 2,3-dioxygenase (IDO), detected at high level in myeloma BM microenvironment, upregulate the expression of PD-L1 on myeloma plasma cells." (PMID 33194767, 2020).